APLN (apelin)
Diseases named in the same sentence as APLN in open-access papers (continued):
Sharing a sentence is not in itself a finding about the gene and the disease.
cognitive decline (3 papers, 2021 to 2025). "Recent evidence has shown that apelin-13, an active form of apelin, suppresses neuroinflammation by inhibiting microglia and astrocyte activation and improves cognitive decline in various pathological processes." (PMID 39954165, 2025). "Recently, evidence shows that apelin-13, an active form of apelin, suppresses neuroinflammation and improves cognitive decline in diverse pathological processes." (PMID 36850004, 2023). "Apelin has not yet been studied in animal models of MS; however, it has been shown to suppress neuroinflammation and cognitive decline in an AD rat model." (PMID 34639186, 2021).
Cushing syndrome (3 papers, 2020 to 2025). Cushing's syndrome (CS) encompasses a group of hormonal disorders caused by prolonged and high exposure levels to glucocorticoids that can be of either endogenous (adrenal cortex production) or exogenous (iatrogenic) origin. "A chordal map was used to visualize the top five KEGG-enriched pathways, including the peroxisome proliferator-activated receptor (PPAR) signaling pathway, cholesterol metabolism, apelin signaling pathway, cytokine‒cytokine receptor interaction and Cushing syndrome." (PMID 38402404, 2024). "The enrichment results revealed significant associations with 31 KEGG pathway terms and 62 GO terms (corrected p < 0.05), including metabolic pathways, Apelin signaling pathway, cGMP-PKG signaling pathway, linoleic acid metabolism, and Cushing syndrome." (PMID 41463551, 2025).
esophageal squamous cell carcinoma (3 papers, 2014 to 2023). Esophageal squamous cell carcinoma (ESCC) is a type of esophageal carcinoma (EC) that can affect any part of the esophagus, but is usually located in the upper or middle third. "We observed tendency to the highest levels of apelin concentration in patients with esophageal squamous cell carcinoma in comparison to patients with gastric adenocarcinoma." (PMID 25049439, 2014). "Any significant relationships with clinic-pathological parameters were demonstrated, but serum apelin concentrations tended to increase in patients with esophageal squamous cell carcinoma." (PMID 25049439, 2014). "An elevated level of APLN in serum correlated with esophageal squamous cell carcinoma metastasis." (PMID 34680307, 2021). "In esophageal squamous cell carcinoma (ESCC), APLN levels were significantly higher in tumor tissue and serum than in healthy controls." (PMID 36614283, 2023).
glomerulosclerosis (3 papers, 2019 to 2024). A hardening of the kidney glomerulus caused by scarring of the blood vessels. "The inhibition of mesangial cell proliferation and fibrosis factor secretion by Apelin is beneficial to improve mesangial cell-centered glomerulosclerosis in DN." (PMID 39014438, 2024). "Apelin treatment attenuated glomerulosclerosis and interstitial fibrosis in agreement with reduced total renal collagen deposition in TGA-PE rats." (PMID 31189936, 2019).
hypothyroidism (3 papers, 2019 to 2025). Abnormally low levels of thyroid hormone. "This study aimed to investigate the complex interactions of thyroid hormone, apelin, and copeptin in the fluid–ion homeostasis of patients with severe transitory hypothyroidism." (PMID 36187132, 2022). "The blood levels of metabolic hormones, including adipokines (insulin, adiponectin, leptin, apelin, chemerin, resistin, visfatin, vaspin, and omentin), in patients with thyroid dysfunction (hyperthyroidism and hypothyroidism) and correlations between thyroid and metabolic hormones." (PMID 40563510, 2025). "Analysis of apelin levels in different TH states revealed that apelin levels were higher in patients with hypothyroidism (4.8 ± 2.5 ng/mL) and hyperthyroidism (3.7 ± 1.9 ng/mL) than in the normal population (3.4 ± 1.4 ng/mL), but the difference was not statistically significant." (PMID 40563510, 2025). "Disturbances in the hypothalamic regulation may explain these findings, e.g., increased TRH secretion being present in hypothyroidism might be responsible for the low apelin level in this state." (PMID 36187132, 2022). "However the data are limited about the level of adipokines such as irisin and apelin – whose metabolic and cardiovascular effects were supposed to be similar to the effects of hypothyroidism – in patients with SCH." (PMID 30864627, 2019). "Moreover, the increase in apelin levels following the correction of hypothyroidism may contribute to the elevation of NT-proBNP due to its hemodynamic effects." (PMID 36187132, 2022).
Impaired glucose tolerance (3 papers, 2014 to 2019). An abnormal resistance to glucose, i.e., a reduction in the ability to maintain glucose levels in the blood stream within normal limits following oral or intravenous administration of glucose. "Apelin KO mice exhibited decreased expression of substrate metabolism‐associated genes/proteins, impaired glucose tolerance, and reduced exercise capacity compared to wild‐type mice, and all of these effects were rescued by hypoxia." (PMID 30868058, 2019).
memory impairment (3 papers, 2019 to 2025). "Repeated i.c.v. treatment with apelin-13 (2 μg/rat/d) ameliorated memory impairment in rats induced by exposure to the forced swim stress using the novel object recognition test, and this action was mediated by the PI3K and ERK1/2 pathways." (PMID 32231577, 2020).
schizophrenia (3 papers, 2020 to 2025). A major psychotic disorder characterized by abnormalities in the perception or expression of reality. "Finally, the apelin signaling pathway has been implicated in schizophrenia, supported by reports of altered apelin levels in patients versus healthy controls." (PMID 41614784, 2025). "Given the increased effect of apelin on locomotor activity in animals, apelin may also associate with a vulnerability for schizophrenia with its direct effects on apelin receptors." (PMID 33033451, 2020). "The levels of ELA and NO of patients with schizophrenia were lower than the levels of ELA and NO in controls, while APLN levels were higher in schizophrenia." (PMID 33033451, 2020). "Recent study indicated that plasma apelin level higher among schizophrenia patients which may be related to severity of mental illness which impact on MetS." (PMID 34895175, 2021). "Decreased levels of ELA and NO and increased APLN levels in schizophrenia suggest that these molecules may be involved in its etiopathology." (PMID 33033451, 2020). "If this study was carried out with newly diagnosed schizophrenic patients who had not taken medication, the diagnostic value of APLN/NO ratio and the relationship between schizophrenia pathogenesis, and the levels of ELA, APLN and NO, would probably have been better understood." (PMID 33033451, 2020). "In conclusion, this novel study investigated the relationship between schizophrenia and ELA and APLN peptides." (PMID 33033451, 2020).
staphylococcus aureus infection (3 papers, 2020 to 2024). An infectious process in which the bacteria Staphylococcus aureus is present. "SKCM VM-related DEGs were mainly enriched in the PI3K-Akt signaling pathway, neuroactive ligand-receptor interaction, cytokine-cytokine receptor interaction, apelin signaling pathway, and Staphylococcus aureus infection." (PMID 38363903, 2024). "In short, these results revealed that DEGs of three clusters were mainly enriched in focal adhesion, the Foxo signaling pathway, and the Apelin signaling pathway for cluster C3 and mineral absorption, neutrophil extracellular trap formation, and staphylococcus aureus infection for cluster C2." (PMID 35096203, 2022).
Tinnitus (3 papers, 2019 to 2023). Tinnitus is an auditory perception that can be described as the experience of sound, in the ear or in the head, in the absence of external acoustic stimulation. "These trends were directionally consistent with the results of the RNA-seq analysis with regard to the lower PREX2 and APLN in VS samples associated with tinnitus." (PMID 37048724, 2023). "Apelin may inhibit the oxidative stress associated with the pathophysiology of idiopathic tinnitus." (PMID 31067839, 2019). "Thus, apelin may be an independent risk factor in the pathophysiology of idiopathic tinnitus, and may be prescribed during follow-up to reduce oxidative stress in the future." (PMID 31067839, 2019). "In the subgroup analysis, the serum apelin levels of the tinnitus patients were significantly lower than those of the control group (96.7 [34.5–152] pg/mL vs 122.6 [52.1–236] pg/mL; P = 0.002), as was the mean HDL level (P = 0.036)." (PMID 31067839, 2019). "The aim of this study was to investigate the apelin mediator as a new oxidative stress parameter in tinnitus patients." (PMID 31067839, 2019). "This is the first pilot study to explore the relationship between the plasma apelin level and tinnitus." (PMID 31067839, 2019). "For example, there was a trend toward greater staining for KCNQ3, NLRP3, and CD68 and lower staining for PREX2 and APLN in the VS samples associated with tinnitus compared to those without tinnitus." (PMID 37048724, 2023). "If apelin, which is abundant in vessel endothelium, plays a role during oxidative ear stress, and if tinnitus were affected by apelin, apelin might exert protective and therapeutic effects." (PMID 31067839, 2019). "We investigated the level of apelin in patients with normal hearing and bilateral tinnitus." (PMID 31067839, 2019). "We found that as tinnitus severity increased, the apelin level decreased." (PMID 31067839, 2019). "Thus, apelin may play a role in the pathophysiology of idiopathic tinnitus, and may be prescribed during follow-up to reduce oxidative stress in the future." (PMID 31067839, 2019). "However, the role of apelin/the APJ system as an oxidative stress mediator in tinnitus is still unknown." (PMID 31067839, 2019). "In fact, since the apelin level of patients with tinnitus was low and decreased as the THI score increased, it is expected to be helpful in the treatment of tinnitus." (PMID 34205595, 2021). "However, the role of the apelin/APJ system as an oxidative stress mediator in tinnitus is unknown." (PMID 31067839, 2019). "Previous studies observed lower mean plasma levels of apelin in patients with tinnitus than in those without tinnitus." (PMID 37048724, 2023). "Apelin expression was lower in VS tumors with tinnitus than it was in those without tinnitus." (PMID 37048724, 2023). "In our study, we found a negative correlation between apelin and tinnitus severity." (PMID 31067839, 2019).
Ureteral obstruction (3 papers, 2019 to 2024). Obstruction of the flow of urine through the ureter. "In a model of unilateral ureteral obstruction, administration of apelin significantly reduced interstitial fibrosis and TGFβ expression." (PMID 31337837, 2019). "Moreover, apelin was found to be upregulated in a model of CKD induced by unilateral ureteral obstruction." (PMID 39200188, 2024). "Indeed, it has been shown that apelin reduced interstitial fibrosis in kidneys of mice following unilateral ureteral obstruction, by attenuating epithelial-mesenchymal transition." (PMID 31337837, 2019).
aortic valve stenosis (2 papers, 2017 to 2021). Aortic valve stenosis (AVS) is a condition characterized by narrowing of the heart's aortic valve opening. "In this study, we aimed to investigate the impact of transcatheter aortic valve implantation (TAVI) on serum apelin levels in patients with severe symptomatic aortic valve stenosis (AS)." (PMID 33113322, 2021). "Apelin may be upregulated compensatorily in the development of aortic valve stenosis." (PMID 29302260, 2017). "The levels of apelin and its receptor APJ are upregulated in patients with calcified aortic valve stenosis." (PMID 29302260, 2017). "As the newest member in the RAAS system, it has been shown that apelin can increase cardiac contractility, lower blood pressure, increase atherosclerotic plaque stability and ameliorate the harmful effects of AT1 receptor activation in the progression of aortic valve stenosis." (PMID 29302260, 2017).
Arthritis (2 papers, 2021 to 2023). Inflammation of a joint. "We found that arthritis rheumatoid acted significantly in macrophages, while apelin signaling pathway enrichment was significant in microglia." (PMID 38274828, 2023).
atopic dermatitis (2 papers, 2013 to 2014). "In conclusion, this preliminary study provides the evidence of significantly higher apelin and decreased level of visfatin in atopic dermatitis." (PMID 23476106, 2013). "The area under the ROC for apelin was 0.981, and for visfatin was 0.988 indicating that serum levels of both adipokines are the best biomarkers differentiating subjects with atopic dermatitis from healthy children." (PMID 23476106, 2013).
bladder tumor (2 papers, 2019 to 2023). "Apelin protein level was overexpressed in bladder tumor tissues compared with paracarcinoma tissues." (PMID 30984306, 2019). "Lastly, our data also showed that apelin was upregulated in bladder tumor tissues compared with matched adjacent noncancer tissues, especially in the high tumor stage, distant metastasis, and vascular invasion." (PMID 30984306, 2019). "Apelin was upregulated in bladder tumor tissues compared with matched adjacent noncancer tissues, especially in the high tumor stage, distant metastasis, and vascular invasion." (PMID 30984306, 2019).
blood pressure (2 papers, 2021 to 2025). "To test our hypothesis, we used an apelin-deficient murine model of adipocyte hypertrophy and high blood pressure, with apelin deficiency generated by knockout of the apelin gene (APL-KO)." (PMID 34782679, 2021).
brain infarct (2 papers, 2019 to 2020). "According to the results, Apelin 13 effectively reduced brain infarct size and ameliorated neurological deficits in a dose-dependent manner." (PMID 30709405, 2019). "Electroacupuncture-induced expression of apelin/APJ mRNA and protein of cerebral vascular endothelial cells in rats with cerebral infarction has an important role in the establishment of blood vessel regeneration and collateral circulation." (PMID 32194492, 2020).
calcification (2 papers, 2011 to 2023). Process by which organic tissue becomes hardened by the physiologic deposit of calcium salts. "This suggests that apelin plays a protective role against arterial calcification." (PMID 21437254, 2011). "Apelin appears to play a protective role against arterial calcification." (PMID 21437254, 2011).
chronic gastritis (2 papers, 2016 to 2022). Inflammation of the stomach that is chronic in nature. "In contrast, the serum Apelin levels remains similar among GC and Chronic gastritis groups (2.84 ± 1.13 vs.2.52 ± 0.78, ng/mL, P = 0.453)." (PMID 27733135, 2016). "Cytoplasmic Apelin staining was identified in 112 of 270 normal gastric mucosa samples and 36 of 81 samples with chronic gastritis (41.2 % vs.44.4 %, P = 0.635)." (PMID 27733135, 2016). "There are a significant difference in Apelin expression status between patients with GC and with chronic gastritis." (PMID 27733135, 2016). "In our study, we found that GC patients had a significantly higher percentage of having strong Apelin staining than samples from chronic gastritis." (PMID 27733135, 2016). "However, the serum Apelin levels remains similar among GC and Chronic gastritis groups." (PMID 27733135, 2016).
chronic pancreatitis (2 papers, 2018 to 2024). A chronic inflammatory process causing damage and fibrosis of the pancreatic parenchyma. "For example, apelin reduces inflammatory cytokines in cerulein-induced chronic pancreatitis, partially through suppression of NF-κB signaling." (PMID 30061611, 2018). "Previous study showed that apelin inhibited the activation of NF-κB which could be the proposed mechanism for diminished values of pro-inflammatory cytokines in the pancreas of mice with chronic pancreatitis that were administered apelin." (PMID 39139157, 2024).
coronary atherosclerosis (2 papers, 2022 to 2024). Atherosclerosis of the coronary vasculature. "Some researchers suggested that apelin reduction is associated with coronary atherosclerosis." (PMID 36199867, 2022). "Extensive studies should support the data to accept that apelin determinates the severity and development of coronary atherosclerosis." (PMID 36199867, 2022). "Apelin may be a novel biomarker for determining the severity and development of coronary atherosclerosis, but extensive studies should support this result." (PMID 36199867, 2022).
edema (2 papers, 2020). An abnormal accumulation of fluid beneath the skin, or in one or more cavities of the body. "Ozone can damage the lungs when inhaled, a recent study showed in a rat model that increased methylation of the apelin promoter downstream of DNA damages the lungs, causing the development of pulmonary edema." (PMID 33145359, 2020). "In a transient model of focal cerebral ischemia, apelin-13 reduces brain injuries and postischemic cerebral edema in a dose-dependent manner, likely through inhibiting neuronal apoptosis, which may be mediated by many mechanisms, such as activating AMPK, PI3K/AKT, and ERK1/2 signaling pathways." (PMID 32194492, 2020).
endometriosis (2 papers, 2018 to 2023). The growth of functional endometrial tissue in anatomic sites outside the uterine body. "Another ovarian pathology that has been recently linked to apelin action is endometriosis." (PMID 29977292, 2018). "Apelin is also highly expressed in glandular cells of the ectopic and eutopic endothelium of women with endometriosis during the secretory phase." (PMID 37424869, 2023).
Epstein-Barr virus infection (2 papers, 2021 to 2023). An infection that is caused by Epstein-Barr virus. "Furthermore, LPS was related to the enrichment of immune system (IL-17 signaling and C-type lectin receptor signaling), infectious disease (Epstein-Barr virus infection), and signal transduction (Apelin signaling) pathways, independently from cell phenotype." (PMID 37680464, 2023).
exfoliation glaucoma (2 papers, 2021 to 2025). "Elevated serum APLN levels are found in patients with age-related macular degeneration, while low levels are observed in those with exfoliative glaucoma." (PMID 39802191, 2025). "With respect to the apelin signaling pathway, studies have reported a decrease in apelin in serum of exfoliation glaucoma patients." (PMID 34156425, 2021).
genitourinary cancers (2 papers, 2021 to 2026). "Expression and role of apelin/APJ signaling in genitourinary cancers, pelvic cancers and other types of cancers." (PMID 33912466, 2021). "Apelin/APj axis was also found to play an important role in genitourinary cancers." (PMID 33912466, 2021). "In genitourinary cancers and pelvic cancers, the apelin/APJ signaling may have important impact." (PMID 33912466, 2021). "The STAT3 signaling pathway and the apelin axis (apelin receptor, APLNR- and ligands, -apelin and/or -elabela), participate in the processes of kidney inflammation and fibrosis and both may be involved in muscle wasting during CKD." (PMID 42016932, 2026).
Hepatitis (2 papers, 2011 to 2017). Inflammation of the liver. "Further analysis of such correlation in CHC groups revealed a positive correlation between TNF-α and apelin in cases of ASC but was nonsignificant after adjustment for covariants, emphasizing the role of covariants in the induction of apelin in early stages of hepatitis." (PMID 22007137, 2011).
Hepatitis B (2 papers, 2021 to 2022). "In addition, the results of KEGG analysis demonstrated that 11 HCC related pathways were mainly enriched in JAK-STAT signaling pathway, human T-cell leukemia virus 1 infection, apelin signaling pathway, and Hepatitis B." (PMID 33456356, 2021).